STATH (statherin)
Description:
Salivary protein that stabilizes saliva supersaturated with calcium salts by inhibiting the precipitation of calcium phosphate salts. It also modulates hydroxyapatite crystal formation on the tooth surface.
Synonyms: STR
Tractability: Antibody: UniProt places it where antibodies can reach, with medium confidence; UniProt predicts a signal peptide or a membrane-spanning region; its Gene Ontology location is reachable by antibodies, with medium confidence.
Gene: Protein-coding gene on chromosome 4 (69,995,966 to 70,002,570, forward strand). Ensembl gene ENSG00000126549.
Subcellular location: Secreted
Gene Ontology:
Molecular function: protein binding; extracellular matrix constituent, lubricant activity; hydroxyapatite binding; structural constituent of tooth enamel
Biological process: antimicrobial humoral immune response mediated by antimicrobial peptide; killing of cells of another organism; negative regulation of bone mineralization; ossification; saliva secretion; defense response to bacterium; regulation of bone mineralization
Cellular component: extracellular region; mitochondrion
Genetic constraint (gnomAD): Loss-of-function variants: 10 observed, 12.42 expected, observed/expected ratio (o/e) 0.81, 90% interval 0.5 to 1.36. The upper end of that interval is the gene's LOEUF score, 1.36, which puts it in group 5 of 6, group 1 being the genes least tolerant of losing a copy. Missense variants: 63 observed, 56.88 expected, observed/expected ratio (o/e) 1.11, 90% interval 0.9 to 1.37. Synonymous variants: 20 observed, 19.28 expected, observed/expected ratio (o/e) 1.04, 90% interval 0.73 to 1.5.
Homologues: Orthologues: chimpanzee STATH (98% identical). Paralogues in human: HTN1 (35% identical), HTN3 (32% identical).
Diseases named in the same sentence as STATH in open-access papers:
STATH is named in the same sentence as 31 diseases in open-access papers, as found by Europe PMC text mining. Sharing a sentence is not in itself a finding about the gene and the disease. The quoted sentences say what the papers report.
dental caries (9 papers, 2012 to 2026). The decay of a tooth, in which it becomes softened, discolored, and/or porous. "Studies have shown that low statherin levels are associated with poor oral health and are correlated with increased dental caries severity and microbial imbalance." (PMID 41552085, 2025). "Other than enzymatic biomarkers, antimicrobial peptides (AMPs) such as cathelicidin peptide LL-37, beta-defensins, statherin and histains also presented significant relationships with dental caries." (PMID 36553087, 2022). "Our GO terms and pathway enrichment analyses further support this idea by revealing that STATH co-expressed genes are associated with oral diseases, specifically periodontitis, which is a known risk factor for HNSCC, and dental caries, which is frequently observed in these patients." (PMID 41552085, 2025). "Salivary proteins such as statherin and HTN have demonstrated several functions that are directly related to the inhibition of dental caries." (PMID 33920657, 2021). "The results indicated strong correlations between high levels of phosphopeptides (PRP 1-3, histatin-1, and statherin) and the absence of dental caries." (PMID 27527350, 2016).
periodontitis (4 papers, 2021 to 2025). An acute or chronic inflammatory process that affects the tissues that surround and support the teeth. "In fact, antibacterial activities against oral pathogens have been demonstrated for statherin and its C-terminal fragments, which retain the specific binding sites for Porphyromonas gingivalis, the keystone pathogen in periodontitis." (PMID 36674470, 2023). "Since periodontitis is recognized as a comorbid condition with COVID-19, altered salivary statherin could negatively influence taste perception." (PMID 39597960, 2024). "Since periodontitis is recognized as a comorbid condition with COVID-19 and could negatively influence taste perception, we assessed salivary statherin." (PMID 39597960, 2024).
calculus (2 papers, 2017 to 2026). "The weak negative correlation between salivary calcium and statherin levels and calculus highlights the potential protective role of statherin against calculus formation, suggesting that statherin activity could be beneficial." (PMID 41522265, 2026). "Hence, the present study was conducted to estimate and correlate salivary statherin and calcium levels in patients with varying degrees of dental calculus formation." (PMID 41522265, 2026). "Salivary statherin exhibited a statistically nonsignificant, modest negative correlation with both calcium concentrations and the development of calculus." (PMID 41522265, 2026). "In the first of the study to compare and correlate the relation between salivary calcium and statherin levels with the amount of dental calculus formation, a weak negative correlation was observed between salivary statherin, salivary calcium levels, and calculus score (r < −0.2)." (PMID 28572822, 2017).
nasal polyp (2 papers, 2018 to 2022). "used DNA microarray technology for the analysis of nasal polyps in CRSwNP patients treated with intranasal glucocorticoids and demonstrated that the expression level of STATH was higher in CRSwNP patients compared with that of normal turbinate mucosa." (PMID 36059464, 2022). "This is contrary to our findings, which may indicate that glucocorticoids can reverse the downregulated expression of STATH in nasal polyp." (PMID 36059464, 2022). "hsa-mir-27a-3p may promote the occurrence of inflammation and the formation of nasal polyps by regulating the expression of AZGP1, NCF2, CCL13, MUC7, PIP, and STATH." (PMID 36059464, 2022).
Cirrhosis (1 paper, 2025). A chronic disorder of the liver in which liver tissue becomes scarred and is partially replaced by regenerative nodules and fibrotic tissue resulting in loss of liver function. "Among these, the statherin-derived peptide DSSEEKFLR demonstrated outstanding discrimination between HCC and cirrhosis (AUC = 0.968), outperforming AFP (AUC = 0.648)." (PMID 41474787, 2025).
diabetes (1 paper, 2021). "The data from those studies suggest that insufficient levels of statherin could contribute to oral cavity complications in diabetes i.e. dental caries and oral infections." (PMID 34212290, 2021).
dyslexia (1 paper, 2024). A learning disorder characterized by an impairment in processing written words. "After excluding STATH from the list of dyslexia risk genes, we meticulously analyzed the data." (PMID 39020327, 2024).
mastitis (1 paper, 2023). Inflammation of breast tissue during lactation or postpartum due to an obstructed duct or infection. "Histatherin is a 6 kDa antimicrobial protein (a chimera of histatin and statherin) naturally present in cow’s milk and associated with mastitis prevention and reduced infection in the newborn calf." (PMID 37016420, 2023).
nephrolithiasis (1 paper, 2018). The presence of a calculus in the pelvis of the kidney; this is most often composed of mineral salts and proteins. "Specific proteins including proline and statherin play an important role in the formation of sialolithiasis, but not in nephrolithiasis." (PMID 29698468, 2018).
oral squamous cell carcinoma (1 paper, 2025). "Complementing our study similar transcriptomic studies reported STATH and MUC7 are downregulated hub genes that regulate key pathways in oral squamous cell carcinoma (OSCC), a major subtype of HNSCC." (PMID 41552085, 2025).
ovarian carcinoma (1 paper, 2022). A malignant neoplasm originating from the surface ovarian epithelium. "Considering that STATH expression is different in both groups, it is possible that the expression of the gene itself and the protein encoded by it, as well as miRNAs regulating its expression, depends on the clinical stage of the ovarian cancer lesions." (PMID 35992817, 2022). "mRNAs corresponding to genes UBA2, GLO1, STATH, and TUFT1, were differentiated in the study samples, irrespective of the stage of ovarian cancer from the control samples, and we decided to focus on them in further analyses." (PMID 35992817, 2022).
salivary gland disorder (1 paper, 2025). A disease involving the saliva-secreting gland. "For example, a study revealed that salivary statherin levels were significantly lower in the saliva of patients with precancerous and cancerous oral lesions than in those of healthy controls, whereas no significant changes were observed in patients with inflammatory or salivary gland disorders." (PMID 41552085, 2025).
tumor (5 papers, 2023 to 2025). "Loss of STATH may compromise these structures and combined with tumor-driven alterations in calcium-dependent and antimicrobial pathways, it could create a salivary microenvironment prone to chronic inflammation, microbial imbalance, and tumor progression." (PMID 41552085, 2025). "Overall, previous findings and our findings complement one another, revealing the downregulation of Statherin at multiple biological layers during tumor progression." (PMID 41552085, 2025). "This downregulation reflects tumor-driven reprogramming of the salivary and oral microenvironments, where suppression of STATH creates a feedback loop that impairs host defenses and promotes tumor progression." (PMID 41552085, 2025). "Differential analysis of 22 paired tumor and normal samples revealed that STATH was significantly downregulated in tumor tissues compared with normal controls (adjusted p=0.004)." (PMID 41552085, 2025). "Therefore, this study aimed to assess STATH as a diagnostic and prognostic biomarker in HNSCC by analyzing its expression in tumor tissues compared with normal tissues, and to explore its potential biological role." (PMID 41552085, 2025). "Together, these findings suggest that decreased STATH is linked to tumorigenesis, reflecting a mechanism by which HNSCC tumors reprogram the salivary microenvironment, which is consistent with the hallmark of cancer tumor microenvironment reprogramming." (PMID 41552085, 2025). "In line with the hallmark of reprogramming of the tumor microenvironment, we hypothesize that HNSCC suppresses STATH expression to remodel the salivary microenvironment, weaken host defense, and promote tumor-supportive inflammation." (PMID 41552085, 2025). "We also propose that HNSCC tumors actively reduce STATH expression, altering the salivary microenvironment in a way that impairs host defense and promotes poor oral health, potentially creating a feedback loop that remodels the tumor microenvironment to favor HNSCC progression." (PMID 41552085, 2025). "We found that STATH is specifically downregulated in HNSCC, with expression significantly lower in tumor tissues compared with normal tissues, but not in other cancer types and significantly varies by ethnicity, age, tumor grade, and nodal metastasis." (PMID 41552085, 2025). "Extracts derived from tumor tissue do not contain peptides derived from statherin (STATH) and three other proteins: submaxillary gland androgen-regulated protein 3b (SMR3B), histatin 1 (HTN1), and histatin 3 (HTN3)." (PMID 39201484, 2024). "The surprising result was that extracts from tumor tissue did not contain peptides derived from salivary gland-specific proteins (STATH, SMR3B, HTN1, HTN3)." (PMID 39201484, 2024). "However, regardless of the tumor type, the effect is the same: a lack of occurrence of peptides derived from proteins STATH, SMR3B, HTN1, and HTN3." (PMID 39201484, 2024). "The lack of identification of peptides from proteins STATH, SMR3B, HTN1, and HTN3 in extracts from tumor tissues may suggest that there is a complete suppression of the production of these proteins in tumor tissues." (PMID 39201484, 2024).
cancer (3 papers, 2014 to 2025). A tumor composed of atypical neoplastic, often pleomorphic cells that invade other tissues. "An assessment of STATH expression levels across 33 cancer types showed that STATH was significantly and consistently downregulated in HNSCC tumors compared with normal controls." (PMID 41552085, 2025). "The last mRNA that was differentiated in the test samples from control samples was the STATH gene, for which we noted decreased expression in cancer samples." (PMID 35992817, 2022). "The mRNA of STATH, RIC8A, and ABCC5 levels were downregulated in cancer samples in comparison to the control samples." (PMID 35992817, 2022). "Although the physiological role of STATH in saliva is well established, its function in cancer biology remains unclear, and no definitive conclusions have been reached." (PMID 41552085, 2025).
STATH also shares sentences with these, for which no sentence is quoted: amyotrophic lateral sclerosis (1 paper); cognitive disorder (1); COVID-19 (1); eosinophilic esophagitis (1); fragile X-associated tremor/ataxia syndrome (1); gingivitis (1); glaucoma (1); head and neck squamous cell carcinoma (1); infection (1); migraine disorder (1); neuralgia (1); neurodegenerative disease (1); Obesity (1); oral diseases (1); peripheral neuropathy (1); sialolithiasis (1); systemic mastocytosis (1).